NARS1 (asparaginyl-tRNA synthetase 1)
Description:
Catalyzes the attachment of asparagine to tRNA(Asn) in a two-step reaction: asparagine is first activated by ATP to form Asn-AMP and then transferred to the acceptor end of tRNA(Asn). In addition to its essential role in protein synthesis, acts as a signaling molecule that induced migration of CCR3-expressing cells. Has an essential role in the development of the cerebral cortex, being required for proper proliferation of radial glial cells.
Synonyms: AsnRS; NARS; NEDMILEG; NEDMILG
Tractability: Small molecule: a structure with a bound ligand is known. PROTAC: ubiquitination databases record sites on it.
Target class: Enzyme; Ligase
Gene: Protein-coding gene on chromosome 18 (57,600,000 to 57,622,213, reverse strand). Ensembl gene ENSG00000134440.
Subcellular location: Cytoplasm
Subcellular location (Human Protein Atlas): Cytosol
Pathways (Reactome):
Metabolism of proteins: Cytosolic tRNA aminoacylation
Gene Ontology:
Molecular function: asparagine-tRNA ligase activity; CCR3 chemokine receptor binding; protein binding; protein dimerization activity; aminoacyl-tRNA ligase activity; ATP binding; nucleic acid binding; nucleotide binding
Biological process: asparaginyl-tRNA aminoacylation; cell migration; cerebral cortex development; tRNA aminoacylation for protein translation; translation
Cellular component: cytosol; extracellular exosome; cytoplasm
Genetic constraint (gnomAD): Loss-of-function variants: 48 observed, 66.43 expected, observed/expected ratio (o/e) 0.72, 90% interval 0.57 to 0.92. The upper end of that interval is the gene's LOEUF score, 0.92, which puts it in group 3 of 6, group 1 being the genes least tolerant of losing a copy. Missense variants: 602 observed, 656.22 expected, observed/expected ratio (o/e) 0.92, 90% interval 0.86 to 0.98. Synonymous variants: 217 observed, 236.33 expected, observed/expected ratio (o/e) 0.92, 90% interval 0.82 to 1.03.
Gene-disease validity (ClinGen):
ClinGen rates the evidence that NARS1 causes each of these diseases.
neurodevelopmental disorder with microcephaly, impaired language, and gait abnormalities (autosomal recessive): Moderate. An autosomal recessive disorder characterized by global developmental delay apparent in infancy.
neurodevelopmental disorder with microcephaly, impaired language, epilepsy, and gait abnormalities (autosomal dominant): Moderate. An autosomal dominant neurodevelopmental disorder characterized by global developmental delay apparent in infancy.
Homologues: Orthologues: chimpanzee NARS1 (99% identical), dog NARS1 (95% identical), macaque NARS1 (95% identical), pig NARS1 (94% identical), mouse Nars1 (94% identical), rat Nars1 (93% identical), rabbit NARS1 (90% identical), tropical clawed frog nars1 (84% identical), zebrafish nars1 (82% identical), Drosophila melanogaster AsnRS (72% identical), Caenorhabditis elegans nars-1 (58% identical). Paralogues in human: NARS2 (25% identical), DARS1 (23% identical), DARS2 (21% identical), KARS1 (19% identical).
Diseases named in the same sentence as NARS1 in open-access papers:
NARS1 is named in the same sentence as 22 diseases in open-access papers, as found by Europe PMC text mining. Sharing a sentence is not in itself a finding about the gene and the disease. The quoted sentences say what the papers report.
microcephaly (11 papers, 2020 to 2024). A congenital or acquired developmental disorder in which the circumference of the head is smaller than normal for the person's age and sex. "Deleterious variants in NARS1 are associated with neurodevelopmental disorder with microcephaly, impaired language and gait abnormalities, which would be consistent with the patient’s phenotype." (PMID 39252027, 2024). "Mutations in NARS1 is associated with various neurodevelopmental syndromes such as microcephaly and cognitive delays, suggesting that regulation of protein synthesis rates is indispensable for development of the nervous system." (PMID 37589291, 2023). "An entirely different molecular cause of microcephaly was recently highlighted through the study of the microcephaly-associated factor NARS1, a Class IIa tRNA synthetase." (PMID 35883578, 2022). "Here, we identify biallelic missense and frameshift mutations in NARS1 in seven patients from three unrelated families with microcephaly and neurodevelopmental delay." (PMID 32788587, 2020). "Together, these results suggest that NARS1 plays a critical role in regulating proliferation of RGCs, leading to microcephaly when deficient." (PMID 32788587, 2020). "Here, the authors identify biallelic NARS1 mutations in individuals with microcephaly and neurodevelopmental delay." (PMID 32788587, 2020). "In order to understand how NARS1 loss leads to microcephaly, we first generated neuronal progenitor cells (NPCs) in 2D cultures, generated from patient-derived iPSCs from two patients and two controls (one from each of MIC-1433 and MIC-2116)." (PMID 32788587, 2020). "Our study identified seven patients from three independent families with recessive microcephaly harboring four pathogenic variants in NARS1, validating NARS1 loss as a cause for human microcephaly." (PMID 32788587, 2020). "Asparaginyl-TRNA synthetase 1 (NARS1) loss also led to microcephaly." (PMID 39062993, 2024). "iPSCs-derived cerebral organoids with mutations in genes KNL1 and NARS1 also displayed a reduction in neural progenitors and defect in the formation of neural rosette structure, which might be relevant to microcephaly." (PMID 34982276, 2022). "Cortical brain organoid modeling recapitulates microcephaly characteristics and scRNA-seq reveals a role for NARS1 in radial glial cell proliferation." (PMID 32788587, 2020). "NARS1 mutations affected gene expression in pathways related to cell cycle (CCND2) and proliferation (KI67), likely contributing to microcephaly." (PMID 32788587, 2020).
neurodevelopmental disorder (6 papers, 2020 to 2024). A behavioral and cognitive disorder with onset during the developmental period that involves impaired or aberrant development of intellectual, motor, or social functions. "Other neurodevelopmental disorders have been linked to three biallelic variants (VARS1, SARS1, NARS1) and one monoallelic variant (NARS1) in cytosolic aaRS genes." (PMID 36330207, 2022). "Neurodevelopmental disorder with microcephaly, impaired language, epilepsy, and gait abnormalities (designated NEDMILEG) is reported to be caused by de novo heterozygous variants in the NARS1 gene." (PMID 36330207, 2022).
tumor (3 papers, 2020 to 2022). "Remarkably, specific aaRS genes do show a DNA profile reminiscent of an oncogene (e.g., GARS1, AIMP2, and YARS2) or tumor suppressor (e.g., NARS1, QARS1, LARS2, and RARS2)." (PMID 33266490, 2020). "Therefore, exploring the tumor suppressor activities of NARS1 and SARS1 represents an interesting direction for future studies." (PMID 33266490, 2020). "NARS1 and SARS1 are also downregulated in two tumor types (LAML for both genes and LUSC and KIRC for SARS1 and NARS1, respectively)." (PMID 33266490, 2020).
cancer (2 papers, 2020). A tumor composed of atypical neoplastic, often pleomorphic cells that invade other tissues. "Similarly, while NARS1 features widespread deletions in cancer genomes, NARS2 is mostly modified through gene amplifications." (PMID 33266490, 2020). "NARS1 and SARS1 stand out as the two most cancer-inhibiting aaRSs." (PMID 33266490, 2020).
infection (1 paper, 2025). The state of being infected such as from the introduction of a foreign agent such as serum, vaccine, antigenic substance or organism. "Deprivation of Asn or knockdown of NARS1, the enzyme charging Asn to tRNA-Asn-AUU, profoundly inhibited 229E infection, but only exerted a mild effect on NL63 or SARS-CoV-2 infection." (PMID 41147596, 2025).
neurological diseases (1 paper, 2025). "Thus, NARS1 variants are associated with a spectrum of dominant neurological diseases." (PMID 40968538, 2025).
NARS1 also shares sentences with these, for which no sentence is quoted: developmental delay (3 papers); melanoma (3); breast carcinoma (2); lung adenocarcinoma (2); adenocarcinoma (1); Alpers syndrome (1); cardiovascular disease (1); colon cancer (1); hearing loss (1); Intellectual disability (1); Leigh syndrome (1); lymph node metastasis (1); metastasis (1); oral cancer (1); Parkinsonism (1); pulmonary arterial hypertension (1).